SPI1 (Spi-1 proto-oncogene)
Diseases named in the same sentence as SPI1 in open-access papers (continued):
Sharing a sentence is not in itself a finding about the gene and the disease.
infection (continued). "We found cytokines like IFNγ, IL-4, IL-13, IFNβ1, TNFα, and transcriptional regulators such as HIF1α, STAT1, CTCF, TP73, IRF1, MXD1, ATF4, SPI1 mediate macrophage activation upon infection." (PMID 35789215, 2022). "Both subpopulations are needed for a productive infection; modeling and in vivo experiments determined that perturbing the ratio of SPI-1− to SPI-1+ cells allows avirulent cheaters to overtake the wild-type S. Typhimurium, and the host to clear the infection." (PMID 36259726, 2022). "The exact mechanism of how the SPI-1 locus contributes to yolk sac infection and colonization remains to be investigated." (PMID 35982923, 2022). "A previous study showed that infection-induced autophagy also contributes to the healing of damaged SCV by SPI1 proteins secreted through theT3SS, helping the endosomal/SCV maturation." (PMID 36061866, 2022). "Salmonella employs two T3SSs during infection, with the SPI-1 T3SS belonging to the Inv-Mxi-Spa T3SS family." (PMID 33875435, 2021). "Accordingly, during the systemic phase of infection and in Salmonella-infected macrophages in vitro, the SPI-1 gene expression is down-regulated." (PMID 33803635, 2021). "For S. Typhimurium, the expression of SPI-1 by only a subpopulation of individuals during infection appears key." (PMID 34154400, 2021). "H-NS is a strong repressor of the genes that encode the type three secretion system and effector proteins in Salmonella pathogenicity island 1 (SPI-1) that Salmonella uses to initiate invasive infection in a host intestine." (PMID 32894292, 2020). "In particular, SPI‐1 effectors are essential for the gastrointestinal stage of the infection, generally involved in invasion of IECs and localised inflammation in the small intestine." (PMID 32185892, 2020). "We note that avrA expression is unchanged during macrophage infection, suggesting its dispensability is reflected in low integration into the SPI-1 regulatory network." (PMID 32316180, 2020). "For S. Typhimurium, the bacterium is also believed to display heterogeneity in terms of SPI1 expression and host adaptation upon infection or when contained in biofilms." (PMID 33330118, 2020). "Connecting the evolutionary history of an infection-relevant pathogenicity island, SPI-1, to extensive experimental characterization of its molecular components helps develop and improve our understanding of pathogen emergence." (PMID 32316180, 2020). "For example, 3D models grown in the RWV successfully recapitulated infection outcomes, such as SPI-1 independent invasion of host cells by S. Typhimurium, as previously observed in vivo." (PMID 32069333, 2020). "During infection, the SPI-1 coded injectisome and effectors are known to mainly induce the rearrangement of host cell actin cytoskeleton to form membrane ruffling, thereby allowing the entry of the bacteria into non-phagocytic cells." (PMID 33101243, 2020). "S. typhimurim grown to stationary phase, which resulted in the reduced expression of SPI-1, elicited similar amounts of IL-1β released from cultured WT and Arhgef2-/- BMDMs at 16-h post-infection." (PMID 32075101, 2020). "SPI-2 supports the SPI-1-driven active infection of human macrophages and intra-macrophage bacterial survival." (PMID 32183199, 2020). "During macrophage infection, the distinct transcriptional profiles of gene modules in and around SPI-1 confirms the phylogenetic evidence for the locus being an archipelago of smaller islands with distinct evolutionary histories and regulatory programs." (PMID 32316180, 2020). "In this study we therefore compared gene expression in the chicken cecum after infection with the wild-type S. Enteritidis and its isogenic SPI1 mutant." (PMID 32404145, 2020). "When the chickens are infected with the SPI1 mutant S. Enteritidis, which is defective in invasion into non-professional phagocytes, most genes induced in the chicken cecum after infection with the wild-type S. Enteritidis are hardly induced." (PMID 32404145, 2020).
infection (continued). "A recent study demonstrated that mutation of the SPI-1 T3SS resulted in decreased HMDM cytotoxicity and IL-1β release, while infection with ΔSPI-2 S." (PMID 31402916, 2019). "We are most likely to observe regulation by CsrA for infection-relevant genes that are highly transcribed in vitro, such as SPI-1, SPI-2, and those involved in central metabolism." (PMID 30682134, 2019). "SPI-2 mutation also resulted in increased expression of SPI-1 effectors detectable by NLRC4 (FljB, PrgI, and PrgJ), suggesting that SPI-2 activity helps suppress the translocation of SPI-1 effectors later in infection." (PMID 31402916, 2019). "Virus yields were determined at 48 h after inoculating MRC-5 and A549 cells with viruses at a multiplicity of infection (MOI) of 0.001 or 0.01 in order to quantify the effects of SPI-1 on replication and spread." (PMID 31145755, 2019). "A negative screen isolating factor required for Salmonella persistence performed by Lawley and colleagues revealed that SPI-1 was necessary for sustaining persistent infection for at least 1 month post infection." (PMID 30857369, 2019). "Among the top hits identified as a Salmonella ligand for APP was integration host factor-α (IhfA) – a protein involved in the regulation of Salmonella SPI-1, a pathogenicity island that contains proteases used for infection." (PMID 30072965, 2018). "invasion of epithelial cell lines, the late exponential phase was shown to be the phase during which Salmonella pathogenesis island-1 (SPI-1) is highly induced, and therefore the more suitable growth phase for infection." (PMID 29019919, 2017). "We envisaged a similar role for the SPI-1 effector SipA as an anti-immune cell factor that protects S. Typhimurium from PMNs arriving in high numbers to sites of infection in the intestine." (PMID 28630067, 2017). "Here, we show that the SPI-2 encoded transcriptional regulator SsrB, which positively controls SPI-2, acts as a dual regulator that represses expression of SPI-1 during intracellular stages of infection." (PMID 28704543, 2017). "Up to 90% of SPI-1 effectors are released extracellularly by S. Typhimurium during infection, indicating that the process of effector release and translocation into host cells is at best wasteful, given our current understanding." (PMID 28630067, 2017). "The extrabacterial release of up to 90% of SPI-1 effectors during infection remains a surprising and unexplained phenomenon, as rather than there being tight cooperative secretion/translocation control of effector expression, it appears to be indiscriminate." (PMID 28630067, 2017). "Following internalization, a subset of bacteria is able to escape the SCV and this unique cytosolic population continues to express T3SS-1 late into infection delivering SPI-1 effectors in a second wave of translocation." (PMID 28848721, 2017). "The T3SS-1 and SPI-1 expressed effector proteins generally help establish infection and play a role in bacterial uptake and generation of the Salmonella containing vacuole (SCV)." (PMID 28848721, 2017). "Even though SopD release is activated under SPI-1 inducing conditions, sopD expression remains elevated during later stages of infection and is involved in survival and replication inside the macrophage." (PMID 29117268, 2017). "All the infections were carried out using invasive bacteria (grown under SPI1-inducing conditions) except long infections (4–16 h) of RAW cells to prevent rapid macrophage pyroptosis induced by invasive bacteria." (PMID 25972862, 2015). "All the mutants and the wild type strain induced inflammatory signaling in the HD11 cell line though the response to SPI1 mutant infection was different from the rest of the mutants." (PMID 26380970, 2015). "We found that under conditions where SPI-1 is downregulated (in vivo infection and in vitro stationary growth phase), both NLRC4- and NLRP3-caspase-1-dependent pathways were activated." (PMID 25879288, 2015).
infection (continued). "According to the different predominant functions related to T3SS1 and T3SS2, the conditions for optimal expression of SPI1 or SPI2 are reached at different moments of the infection." (PMID 25972862, 2015). "Once inside the host, the expression of both flagella and Spi1 appear to be downregulated but not abolished with most of the cytosolic population expressing both flagella and Spi1 at latter stage of infection." (PMID 24603858, 2014). "In ΔadhE::kan, seven SPI-1 genes were up-regulated at 1 h post-infection, with relative expression values ranging from 1.15 to 3.16 fold over the wild-type." (PMID 23442379, 2013). "The T3SSs encoded by SPI-1 and SPI-2 are both essential for infection in chickens, pigs and cattle, although there are some mutants within both regions that are not attenuated or exhibit a less pronounced phenotype in chickens." (PMID 23637626, 2013). "The initial stages of infection by the pathogen are controlled by the genes of SPI-1, which enable the pathogen to invade the epithelial cells of the intestine and induce an inflammatory response." (PMID 24079299, 2013). "The response of SPI-1 after infection with HCT-8 cells was determined by using qPCR on the same panel of 19 genes." (PMID 23442379, 2013). "Various SPI-1 genes in the mutants were up-regulated over the wild-type as early as 1 h and lasting until 24 h post-infection." (PMID 23442379, 2013). "In a challenge with human HCT-8 and THP-1 cell lines, SPI-1 gene expression was also significantly altered from the wild-type at various times post-infection." (PMID 23442379, 2013). "At 18 h post-infection, six SPI-1 genes were found to be up-regulated, with fold changes of 1.85 to 3.21 over the wild-type." (PMID 23442379, 2013). "Only MMP7 was significantly induced in the cecum 4 days after the infection with the Salmonella Enteritidis SPI1 mutant." (PMID 23687968, 2013). "For instance, SPI-1 and SPI-2, each encoding genes for a type III secretion system (T3SS), were shown to be necessary for in vitro and in vivo infection of cell lines, C. elegans, mice or calves." (PMID 23951347, 2013). "The two T3SS are encoded on separate pathogenicity islands, SPI-1 and -2, with SPI-1 more strongly associated with the intestinal phase of infection, and SPI-2 with the systemic phase." (PMID 23950998, 2013). "At 4 h post-infection, 14 of the 19 SPI-1 genes tested (74%) were down-regulated, with prgJ having the lowest magnitude of the fold-change at −1.67 and sipB having the highest magnitude of the fold-change at −4.44 under the wild-type." (PMID 23442379, 2013). "At 6 h post-infection, 16 of the 19 SPI-1 genes tested (84%) were down-regulated, with orgB having the lowest magnitude of the fold-change at −1.31 and sipB having the highest magnitude of the fold-change at −3.58 under the wild-type." (PMID 23442379, 2013). "By 24 h post-infection, SPI-1 genes were either down-regulated in both mutant strains, or not significantly different from the wild-type strain." (PMID 23442379, 2013). "Several SPI-1 genes were up-regulated after HCT-8 cell challenge, from 1 h post-infection lasting to 24 h post-infection when SPI-1 expression in the mutants decreased compared to the wild-type." (PMID 23442379, 2013). "We have previously shown that cultured epithelial cells undergo a significant transcriptional reprogramming shortly after infection with S. Typhimurium that is strictly dependent on the function of its SPI-1 T3SS." (PMID 24098123, 2013). "After infection with the SPI-1 mutant the initial activation at 15 and 30 MAI, remained until 60 MAI." (PMID 22812426, 2012). "While epithelial cells were invaded by the SPI1-mediated macropinocytosis, the infection of macrophages was mediated by phagocytosis of non-invasive bacteria." (PMID 22427996, 2012). "This study especially showed that SPI-1- and flagella-related genes were expressed inside epithelial cells at later stages of the infection than in macrophage-like cells." (PMID 23170225, 2012).
infection (continued). "We next sought to determine the impact of infection with the SPI-1 and SPI-2 mutant strains on the composition of the gut microbiota." (PMID 23155475, 2012). "The different infection procedures are required, since SPI1-mediated invasion of phagocytic cells induces a rapid form of apoptotic cell death that interferes with the quantification of intracellular replication." (PMID 22427996, 2012). "One explanation for such results is that deletion of SPI-1 genes suppresses the hilA infection defect and allows Salmonella to colonize and infect their hosts in a SPI-1-independent manner." (PMID 23170225, 2012). "Accordingly, experiments addressed at elucidating the roles of these polyamines in infection revealed that expression of genes from both of the major virulence loci SPI1 and SPI2 responded to exogenous polyamines and was reduced in the polyamine mutant." (PMID 22558361, 2012). "Infection studies in embryos that lack macrophages due to knockdown of the Spi1/Pu.1 transcription factor showed that macrophages do restrict the growth of M. marinum, but also are essential for spreading of M. marinum into embryonic tissues." (PMID 21366518, 2011). "Although these mutant strains had normal proliferation rates when grown in LB medium, the proliferation of these mutants in plants were strongly reduced, indicating that both SPI-1- and SPI-2-encoded apparatuses are necessary to establish robust infection." (PMID 21915285, 2011). "Translocation into macrophages under non-invasive conditions was mainly dependent on the SPI-2-encoded type III secretion system but some participation of the SPI-1 system was also detected 6 hours post-infection." (PMID 22046414, 2011). "Infections with any of the mutants harbouring SPI-2 (including the mutant in which we left only SPI-2 but removed SPI-1, SPI-3, SPI-4 and SPI-5) resulted in fatalities, liver injures and NK cell depletion from the spleen." (PMID 20226037, 2010). "Our results complement and further extend previous findings of the expression of these SPI-1 factors, and demonstrate the importance of examining protein expression in vivo in the context of infection." (PMID 19371445, 2009). "We have taken a mixed infection approach to study the contribution of SPI1 and SPI2 to the colonization of the chicken by Typhimurium." (PMID 19126220, 2009). "The involvement of SPI-1 was a novel finding since that island had previously been thought to be involved only in the gastrointestinal phase of infection." (PMID 19649318, 2009). "We have taken a mixed infection approach to study the role of SPI1 and SPI2 in the colonization of the chicken by Typhimurium." (PMID 19126220, 2009). "We investigated the importance of SPI-1, encoding the TTSS-1, in colonization of the cecum during serotype Typhimurium infection in White Leghorn chicks and Salmonella-resistant mice." (PMID 18922185, 2008). "For conditions mimicking an early infection stage [LB cultures], SPI-1, SPI-4 and SPI-5 are identified as significantly regulated in one or both mutants [hfq and smpB]." (PMID 18986519, 2008). "We compared the expression of edin following infection of wild-type flies with wild-type Salmonella typhimurium or a SPI1, SPI2 mutant strain of Salmonella that has decreased pathogenicity." (PMID 18654628, 2008). "Our finding that SipA persists after Salmonella entry reinforces the view that SPI1 effectors not only trigger bacterial uptake but also remain active later during infection." (PMID 18005682, 2007). "However, the importance of the SPI-1 injectisome in infection of professional phagocytes such as macrophages, the predominant host cell type supporting systemic infection, is less clear." (PMID 41188240, 2025). "To determine if these factors influenced control of NEDD9 expression, we next analyzed NEDD9 protein levels upon infection of mBMDM with ST Salmonella Pathogenicity Island SPI1 (ΔinvA) and SPI2 (ΔssaV) mutants, which have defects in the main type III secretion system (T3SS)." (PMID 40506423, 2025).
infection (continued). "This hypothesis is further supported by previous studies indicating that SPI-1 contributes more significantly to infection of poultry by S. enterica than SPI-2." (PMID 40005504, 2025). "Here we paired ribosome profiling with RNA-Seq during infection of macrophages by wild type (WT) or SPI-1 injectisome mutant Salmonella to understand the regulation at the transcriptional and translational levels of the dynamics of gene expression driven by injectisome-dependent infection." (PMID 41188240, 2025). "Coordinating SPI1 regulation and downregulation of OmpD by InvR and MicC might lessen any stress in outer membrane assembly during infection." (PMID 40013798, 2025). "We reason that InvR-mediated post-transcriptional regulation of hilA might be too subtle in the overall context of SPI1 regulation to observe a strong phenotype in the animal model of infection." (PMID 40013798, 2025). "SopD can be secreted during the early stages of infection by the SPI-1 T3SS." (PMID 38673776, 2024). "SPI-1 plays an important role in the invasion of the host cellular cytosol, intracellular survival, and induction of cellular apoptosis in vitro, but it does not seem to be required for cytokine storm induction in an in vivo infection model." (PMID 37325511, 2023). "SPI-1 is in several respects important during the intestinal phase of the infection." (PMID 35127930, 2022). "Although the functional consequences of SPI-1 heterogeneity for infection are well established, due to the complexity of the host environment and technical challenges associated with in vivo measurements, less is known about the extent to which input variables can tune the response." (PMID 36259726, 2022). "Besides allowing the host cell invasion during the early phase of infection, SPI-1 is also involved in the induction of macrophage apoptosis." (PMID 33803635, 2021). "Another SPI-1 essential effector protein is SopB, which avoids the apoptosis of human epithelial cells due to the inhibition of the mitochondrial ROS production generated by the typical response to the infection." (PMID 34276584, 2021). "SPI-1, located at centisome 63 encoding predicted type III secretion system (T3SS), is a fundamental complex of genetic elements necessary during the initial stages of infection." (PMID 34603240, 2021). "Thus, far our data point toward an upregulation of KDM6B and a decrease in H3K27me3 mark during infection of host cells with Salmonella having functional SPI1 loci." (PMID 34696686, 2021). "However, the other mechanism is SPI-1-independent, and characterized by a delayed induction of apoptosis to kill infected macrophages as late as 18 h post-infection." (PMID 32183199, 2020). "If sitABCD and SPI-1 do cooperate during infection, their physical proximity on the genome may be purely coincidence." (PMID 32316180, 2020). "There are conflicting reports on whether sitABCD is essential for SPI-1 virulence, but the majority argue that is it required for infection." (PMID 32316180, 2020). "Similarly, birds administered with an SPI-1 deletion mutant Salmonella Typhimurium vaccine strain did not exhibit significant antibodies titres following vaccination, but did following infection with a wild-type strain." (PMID 33228065, 2020). "To this end, we infected zebrafish embryos with a SipB-deficient S. Typhimurium strain, which fails to produce the translocation apparatus for delivery of SPI1 effectors, resulting in severe inability to cause infections in non-phagocytic cells." (PMID 31428591, 2019). "During the process of infection, Salmonella uses two specialized nanomachines known as Type 3 Secretion Systems (T3SS) that are encoded by Salmonella Pathogenicity Island-1 (SPI-1) (Collazo and Galán, 1997) and SPI-2, respectively, to inject virulence factors directly into host cells." (PMID 31214517, 2019).